KRAS (KRas proto-oncogene, GTPase)
Diseases named in the same sentence as KRAS in open-access papers (continued):
Sharing a sentence is not in itself a finding about the gene and the disease.
colorectal cancer (continued). "For example, activation of the IGFR1R has been shown to be essential in KRAS-mutant-mediated PI3K activation in Non-Small Cell Lung Cancer (NSCLC) and colorectal cancer (CRC), whereas EGFR appears to have strong importance in KRAS-WT-mediated PI3K activation in NSCLC models." (PMID 39372214, 2024). "Furthermore, based on the corresponding Colorectal Cancer Subtype Consortium analysis of a comprehensive CRC dataset, the authors showed that male KRAS*CRC patients had lower survival rates than female KRAS*CRC patients." (PMID 38222317, 2024). "Comprehensive genomic analyses have demonstrated that KRAS, one of the three major RAS oncogenes, is frequently altered in multiple types of cancer, including colorectal cancer (CRC), non-small cell lung cancer (NSCLC), and pancreatic ductal adenocarcinoma (PDAC)." (PMID 38756650, 2024). "The prevalence of Kirsten rat sarcoma viral oncogene (KRAS) mutations in MOC is slightly higher compared to mucinous and non-mucinous colorectal carcinomas, with mutations observed in 43–46% of MOC cases versus 30% of mucinous colorectal tumors." (PMID 39040449, 2024). "KRAS-mutant tumors were shown to reprogram macrophages to promote therapeutic resistance and malignant progression by driving the production of CSF2 and lactate in colorectal carcinoma." (PMID 38618956, 2024). "AI applied to radiologic images, called radiomics, was also evaluated to predict the MSI status in colorectal cancer with no exploration of BRAF and KRAS mutation status." (PMID 38201408, 2023). "It is known that EGFR inhibition is not effective in KRAS-mutant colorectal cancers, due to downstream activation of the pathway." (PMID 37190303, 2023). "However, another study indicated that colorectal cancer patients with a 2.3~10% KRAS mutant allele burden in tumor tissue might be resistant to anti-EGFR therapy, and suggested that a >2.3% MAF detected in tumor tissue should be considered positive for KRAS mutation." (PMID 37511664, 2023). "Similarly, recent trials have shown that colorectal cancer and NSCLC seem to respond differently to AMG510 although these cancers share KRAS G12C." (PMID 36910668, 2023). "The first approved, EGFR inhibitor erlotinib in combination with gemcitabine, gave a modest survival benefit compared to gemcitabine alone and was effectively abandoned by the community after negative data in KRAS-mutant colorectal cancer emerged." (PMID 37927794, 2023). "Common examples are HER2 in breast and gastric cancers, EGFR in lung, colorectal, and head and neck cancers, KRAS in colorectal, pancreatic, and lung adenocarcinoma, BRAF in melanoma and colorectal cancer, ALK in some NSCLC cases, and PSA as a prostate cancer biomarker." (PMID 38202898, 2023). "Despite the high mutation frequencies of KRAS, NRAS, and BRAF in colorectal cancer (CRC), there are no effective and reliable inhibitors for these biomarkers." (PMID 37063257, 2023). "For colorectal cancer, ribosomal biogenesis has been regarded as the integrator or final effector of the major altered signaling pathways in tumorigenesis, such as MYC and KRAS." (PMID 37373047, 2023). "On the other hand, the 20050181 study showed significant OS and PFS benefits of panitumumab (Pmab) plus FOLFIRI vs. FOLFIRI for KRAS-wild colorectal cancer, whereas no OS benefit was observed for KRAS-mutant colorectal cancer." (PMID 37760533, 2023).
colorectal cancer (continued). "In addition, the activation of the EGFR pathway and its downstream effectors KRAS and PI3K can trigger multiple signaling pathways, such as proliferation and angiogenesis, in colorectal cancer." (PMID 37465677, 2023). "drugs that do not develop the resistance caused by the mutation of KRAS and APC should be adopted preferentially in the therapy of colorectal cancer." (PMID 37368936, 2023). "However only a minority of patients with lung cancer respond to ICB and other KRAS-mutant cancers including PDAC and (MMR-proficient) colorectal cancer have shown little benefit." (PMID 37581538, 2023). "In line with this, overexpression of PCSK9 predicts shorter survival for colorectal cancer patients with APC and KRAS mutations, but not for colorectal cancer patients with only the APC mutation." (PMID 37958351, 2023). "Interestingly, GALNT6 mRNA expression showed significant correlation with KRAS and BRAF status in early-stage colorectal cancers." (PMID 35692787, 2022). "Furthermore, the SuPAR may predict response to therapy in colorectal cancer patients, as patients with low levels of circulating suPAR and a wild-type KRAS tumor benefit from treatment with oxaliplatin and cetuximab, as compared to patients with wild-type KRAS and high levels of SuPAR." (PMID 35493073, 2022). "We showed that phospho‐ERK1/2 and phospho‐Akt1/2/3 are not upregulated in colorectal cancer (CRC) tumors compared to matched mucosa, regardless of KRAS mutation status." (PMID 34919787, 2022). "For example, for common tumours such as colorectal cancer where there is an ever-expanding list of clinically relevant biomarkers (e.g., BRAF V600E, MMR, HER2, POLE, KRAS G12C, NTRK), each patient subset represents only a small proportion of the overall population." (PMID 36077668, 2022). "Somatic hotspot mutations KRAS p.G12C and PIK3CA p.Q546K are associated with colorectal cancers from biallelic MUTYH carriers compared with non-carriers (p = 2 × 10−23 and p = 6 × 10−11, respectively)." (PMID 35668106, 2022). "What is the association of simultaneous vs delayed resection of liver metastases with major complications and survival in adults with colorectal cancer with or without KRAS sequence variation?" (PMID 36121654, 2022). "In contrast to KRAS mutations, mutations of the gene encoding for the catalytic sub-unit alpha of kinase PI3K, PIK3CA, which are common in colorectal cancer are not mutually exclusive with BRAF mutations." (PMID 36079062, 2022). "In vitro characterization of the imaging and therapeutic agent showed low nanomolar binding to EGFR-positive colorectal cancer and breast cancer cells with (DLD-1, SNU-C2B, SW620) or without (HT-29 and MDA-MB-231) mutations in KRAS." (PMID 36145664, 2022). "A systematic review of 1779 patients concluded that in patients with KRAS‐positive colorectal cancer, plasma KRAS‐positive status can be a negative prognostic factor in terms of overall survival, progression free survival, and disease‐free survival." (PMID 35312176, 2022). "Previous studies of ctDNA in colorectal cancer patients have demonstrated a positive selection of mutant KRAS clones during epidermal growth factor receptor (EGFR) blockade, and a decline in mutant KRAS clones upon the withdrawal of the therapy." (PMID 35273301, 2022).
colorectal cancer (continued). "Testing the efficacy of these and additional drug candidates, such as those shown to inhibit oncogenic KRAS and HIF pathways in a colorectal cancer screen, in treating oncogenic RAS in model systems like our fly are urgently needed to identify valuable treatment options in the clinic." (PMID 34580712, 2022). "Colorectal cancer cells show increased basal phosphorylation of EGFR and respond to EGF by activating MAPK signaling, even in the presence of an activating KRAS G12C mutation that is not observed in NSCLC cells." (PMID 35267628, 2022). "Kirsten rat sarcoma viral oncogene homolog (KRAS) is a well-known oncogene that drives cancer progression to metastases in various types of carcinomas, including non-small cell lung cancer (NSCLC), pancreatic cancer, and colorectal cancer." (PMID 36348317, 2022). "Colorectal cancer cells were all highly sensitive to killing by reovirus-activated NK cells regardless of KRAS genotype or EGFR expression level, and reovirus further enhanced NK-cell cytotoxicity against cetuximab-coated colorectal cancer cells." (PMID 33933132, 2021). "Given that KRAS G12C inhibitors did not result in good response rates for colorectal cancer patients in clinical trials, we conducted in vivo evaluation of the combined KRAS G12C and FAK inhibition therapy using two CRC PDX models: CO‐04‐0315 and CO‐04‐0070." (PMID 34151545, 2021). "Unlike the routine detection of HER2, EGFR, BRAF, KRAS and other genes in breast cancer, lung cancer, colorectal cancer and other tumors, HCC has not yet an apparent gene-phenotype related to its prognosis and treatment due to its heterogeneity." (PMID 35071004, 2021). "Some genes do manifest this type of selectivity (e.g., broad dependence on CTNNB1 in colorectal cancer, MYB in leukemia, IRF4 in multiple myeloma, KRAS in pancreatic cancer, and SOX10 in skin cancer), but such common essentiality within a lineage is relatively unusual." (PMID 33554860, 2021). "The referenced papers were selected through a PubMed search performed on 11 March 2021 with the following searching terms: KRAS and non-small cell lung cancer (NSCLC), or colorectal cancer (CRC), or pancreatic cancer, or low-grade serous ovarian carcinoma (LGSOC), or endometrial cancer (EC)." (PMID 34064352, 2021). "In analyses stratified for molecular subtypes, MIC A/B was associated with a lower risk of KRAS-mutated colorectal cancer (OR: 0.66, 95% CI 0.47–0.93), no proteins were associated with the risk of BRAF-mutated or KRAS-BRAF-wild type colorectal cancer." (PMID 33664295, 2021). "Although serum tumor markers (STMs), clinicopathological characteristics and the status of KRAS and MMR play an important role in optimizing the treatment and prognosis of colorectal cancer, their interrelationships remain largely unknown." (PMID 34221952, 2021). "Japanese studies suggest less expensive ways of treating colorectal cancer, such as the use of KRAS test before a particular chemotherapy as opposed to KRAS preselection test; however, further studies are needed to ascertain its effect." (PMID 34574371, 2021). "Oncogenic KRAS was shown to inhibit the expression of STAT1, STAT2 and IRF9 (members of the ISGF3 transcription-promoting complex); thus, hampering the basal and IFN-induced expression of ISGs in colorectal cancer cell lines." (PMID 33668131, 2021). "Indeed, the combination of the KRAS-G12C inhibitor MRTX1257 and the EGFR antibody cetuximab is being explored in a phase III trial in patients with advanced colorectal cancer (NCT04793958)." (PMID 34200676, 2021).
colorectal cancer (continued). "In the present study, we focused on the translational potential of RGS in KRAS-mutant colorectal cancer treatment; the selective anti-tumor effect of RGS in KRAS mutant CRC was comprehensively studied, for the first time, in models ranging from cancer cell lines to patient-derived xenograft models." (PMID 34347396, 2021). "Recently, oncogenic KRAS was found to promote an immunosuppressive tumor microenvironment through the CXCL3‐CXCR2 pathway in MDSCs, providing a potential combination therapeutic strategy for the treatment of advanced colorectal cancer." (PMID 33283987, 2021). "In addition, recent studies have shown that furin can activate some tumor-related protein precursors in the KRAS-related ERK-MAPK pathway, thus promoting tumorigenesis of colorectal cancer." (PMID 33968987, 2021). "For instance, loss of EZH2 was shown to promote genomic instability, to act as a barrier to KRAS-driven inflammation and EMT or to promote therapy resistance in BC, colorectal cancer, lung cancer, acute myeloid and T-cell acute lymphoblastic leukemia, respectively." (PMID 34845197, 2021). "The presence of KRAS/NRAS mutations suggests the lack of response to EGFR‐targeted therapies for patients with NSCLC, head and neck cancer or colorectal cancer." (PMID 34658138, 2021). "Preclinical evidence suggests that KRAS activation may predict sensitivity to MEK inhibitors, such as trametinib and cobimetinib tested in colorectal cancer." (PMID 33435376, 2021). "In addition, miR-84 suppressed cell proliferation, migration, and metastasis in renal cell carcinoma and colorectal cancer by targeting and interacting with RAB23 and KRAS/CDC42 axis, respectively." (PMID 33817254, 2020). "It was reported that the downregulation of ZC3H13 expression regulated KRAS and ERK signaling expression, which could inhibit the invasion and proliferation of colorectal cancer cells." (PMID 32733931, 2020). "Moreover, the most popular genes were APC (in Wnt pathway), KRAS (in MAPK pathway) and PIK3CA (in PI3K pathway) in the colorectal cancer, pancreatic cancer, and gastric cancer while they were beta-catenin and CTNNB1 in liver cancer." (PMID 33127962, 2020). "In colorectal cancer liver metastases (CLM), KRAS status was available in 69 patients." (PMID 32867151, 2020). "A 55-year-old patient with KRAS and BRAF wild-type advanced colorectal cancer had 100% ATM IHC loss in his tumor, but NGS did not detect an ATM mutation." (PMID 32568634, 2020). "Detection of ctDNA has demonstrated its relevance in lung or colorectal cancer with the detection of EGFR and KRAS mutations for non-invasive tumors genotyping, treatment response follow-up, and relapse prediction." (PMID 33042820, 2020). "Furthermore, Vc has been suggested to kill KRAS and BRAF mutant colorectal cancer cells by targeting GAPDH20." (PMID 30774978, 2019). "KRAS is an independent negative predictor for anti-epidermal growth factor receptor (anti-EGFR) treatment in colorectal cancers (CRCs)." (PMID 31729406, 2019).
colorectal cancer (continued). "Hence, we inferred that hsa-miR-224-5p-CXCR4/SMAD4/KRAS interactions play a pivotal role in the development of RSCOAD and LSCOAD by regulating pathway of intestinal immune network for IgA production and colorectal cancer." (PMID 31073530, 2019). "Many laboratories find this easier as lung cancer cases can be batched with other (e.g. colorectal cancer) cases undergoing KRAS testing, rather than waiting for sufficient EGFR or ALK testing samples." (PMID 30470932, 2019). "In contrast, the APC mutant and KRAS WT COLO320DM colorectal cancer cell line did not reduce growth or change canonical WNT activity upon treatment with the MEKi, neither alone or in combination with the TNKSi." (PMID 30717152, 2019). "In colorectal cancer, the genes that were significantly enriched for copy number gain in TCGA versus GENIE were BRCA2 (60% versus 23%, p < 0.0001), BRAF (48% versus 11%, p < 0.0001) and KRAS (22% versus 3%, p < 0.0001)." (PMID 30728399, 2019). "Targeted sequencing of individual genes to guide therapy has become the standard of care for several different cancer types, including colorectal cancer (KRAS, BRAF, and NRAS), lung cancer (KRAS and EGFR), melanoma (BRAF), GI stromal tumor (KIT), and gliomas (IDH1 and IDH2)." (PMID 32914008, 2019). "Across the different cancer models, four out of sixteen cell lines: colorectal carcinoma cell line Colo-205, pancreatic cancer cell line MiaPaca-2 and lung cancer cell lines NCI-H460 and PC9 had robust knockdown of KRAS mRNA with a low IC50 (<600 nM) in response to AZD4785 treatment." (PMID 30927008, 2019). "A greater understanding of colorectal cancer biology followed by use of EGFR-targeted treatments has led to discovery of the importance of BRAF, PIK3CA, KRAS, and NRAS mutations in predicting a lack of response to EGFR-targeted therapy." (PMID 29254887, 2018). "Currently, KRAS and BRAF mutations are not seen as “only” altering signaling during the development of colorectal cancer." (PMID 29907857, 2018). "Approximately half of the patients with wild-type (WT) KRAS colorectal carcinoma do not respond to these therapies." (PMID 30344942, 2018). "MiR-143-3p has been shown to target KRAS and IGF1R in colorectal cancer." (PMID 29137392, 2017). "The fact that STK11ex1-2 mutations were also associated with KRAS mutations might be related to a shared risk factor (tobacco) or an oncogenic cooperation between both alterations as for BRAF or KRAS with PIK3CA in lung and colorectal cancer." (PMID 26625312, 2017). "Unlike let-7 and miR-143, miR-31 has been shown to negatively regulate KRAS inhibitor RASA1; thus, miR-31 could be a potent enhancer of KRAS in colorectal cancer." (PMID 28441730, 2017). "Together, we showed feedback HER3 activation upon cetuximab treatment in KRAS and BRAF colon cancer cells together with induction of HER2:HER3 heterodimers, which could potentially result in cetuximab resistance in colorectal cancer patients." (PMID 28032592, 2017). "Treatment with gelam honey (40–100 mg/mL) alone and in combination with ginger (honey 10–50 mg/mL plus ginger 3 mg/mL) led to downregulation of Kirsten rat sarcoma viral oncogene homolog (KRAS), extracellular signal-regulated kinase (ERK), and Akt genes in the colorectal cancer cell line HT29." (PMID 28933410, 2016). "Somatic mutations in KRAS (codons 12, 13) and BRAF (V600E) in colorectal cancer predict poor prognosis and nonresponse to anti-EGFR antibodies." (PMID 27193446, 2016). "In the metabolomic analysis using control and KRAS knockdown DLD1 cells, which can survive under glucose-deprived conditions, we found that the metabolism of colorectal cancer did not depend on KRAS mutation alone but depended on the medium condition as well." (PMID 27924922, 2016). "Recurrent mutations in CDH10 have recently been reported in EGFR/KRAS/ALK mutation-negative lung adenocarcinoma in never-smokers and as a prognostic mutation signature in colorectal cancer." (PMID 27093186, 2016).